IRAIN (IGF1R antisense imprinted non-protein coding RNA)
Synonyms: IGF1R-AS; IGF1R-AS1
Gene: Long non-coding RNA gene on chromosome 15 (98,572,365 to 98,648,337, reverse strand). Ensembl gene ENSG00000259424.
Diseases named in the same sentence as IRAIN in open-access papers:
IRAIN is named in the same sentence as 8 diseases in open-access papers, as found by Europe PMC text mining. Sharing a sentence is not in itself a finding about the gene and the disease. The quoted sentences say what the papers report.
acute myeloid leukemia (5 papers, 2015 to 2022). Acute myeloid leukemia (AML) is a group of neoplasms arising from precursor cells committed to the myeloid cell-line differentiation. "Similarly, a study also showed downregulation of lncRNA IRAIN in non-M3 acute myeloid leukemia clinical specimens." (PMID 32983957, 2020). "Clinical data further support the suggested tumor-suppressive function of IRAIN in AML, demonstrating a correlation between low IRAIN expression and poor prognosis in non-M3 acute myeloid leukemia patients." (PMID 35596093, 2022). "Another lncRNA involved in acute myeloid leukemia (AML) is IRAIN, which is produced from the insulin-like growth factor type I receptor (IGF1R) imprinted locus." (PMID 25927065, 2015). "There have identified a number of lncRNAs association with several subtypes of leukemia, such as MEG3, IRAIN, and UCA1 related to acute myeloid leukemia (AML) and ANRIL, LUNAR1, in ALL." (PMID 34101758, 2021). "It is reported that in non-APL acute myeloid leukemia patients, diminished expression of IRAIN results not only in shorter OS but also in a refractory response to chemotherapy." (PMID 36362925, 2022).
pancreatic cancer (4 papers, 2018 to 2023). "There was significant IRAIN up regulation in pancreatic cancer tissues that was associated with larger tumor sizes, higher TNM stages, and lymph node metastasis." (PMID 37807067, 2023). "In pancreatic cancer, the lncRNA IRAIN inhibits the expression of the downstream target KLF2 by binding to LSD1 and EZH291." (PMID 37781524, 2023). "The LncRNA IRAIN was found to be highly expressed in pancreatic cancer, and its high expression predicted advanced pathological stage, larger tumor size, and lymph node metastasis." (PMID 37781524, 2023). "LncRNA IRAIN stimulates anti-apoptosis and proliferation via methylation-dependent repression of Kruppel-like factor 2 and P15 in pancreatic cancer cells." (PMID 32983957, 2020). "Interestingly, a previous study identified both oncogenic and anti-oncogenic roles for IRAIN, an lncRNA involved in a variety of cancers including breast cancer, non-small cell lung cancer, and pancreatic cancer." (PMID 32983957, 2020). "IRAIN induced cell proliferation directly through interacting with EZH2 and LSD1 complexes and suppressing KLF2 and P15 in pancreatic cancer cells." (PMID 37807067, 2023). "In our previous studies, we demonstrated that lncRNA IRAIN suppressed apoptosis and promoted cellular proliferation by binding to LSD1 and EZH2 in pancreatic cancer." (PMID 30367681, 2018). "Targeting IRAIN, LSD1, or EZH2 may be a potential approach to treat pancreatic cancer." (PMID 37781524, 2023).
breast carcinoma (3 papers, 2014 to 2020). "Our findings were in support of the current literature, which clarified that upregulation of lncRNA IRAIN transcription triggered repression of cell proliferation, migration, and invasion in breast cancer cells." (PMID 32983957, 2020). "The presence of full-length IRAIN lncRNA was further confirmed by northern blotting in three breast cancer samples." (PMID 25092925, 2014). "With the rebalance of the IGF-1R/IRAIN ratio by depletion of IRAIN using the CRISPR system, breast cancer cells exhibited a significant reduction in proliferation, migration, and invasion capacities." (PMID 31847392, 2019).
leukemia (2 papers, 2014 to 2019). A malignant (clonal) hematologic disorder, involving hematopoietic stem cells and characterized by the presence of primitive or atypical myeloid or lymphoid cells in the bone marrow and the blood. "In cDNA samples, however, only the ‘A’ allele was detected (lanes 3 and 6), indicating that IRAIN lncRNA is monoallelically transcribed in KG-1 leukemia cells." (PMID 25092925, 2014). "In summary, we have identified IRAIN as a novel lncRNA that is downregulated in leukemia cell lines and in patients with high-risk AML." (PMID 25092925, 2014). "In addition, IRAIN was downregulated both in leukemia cell lines and in blood obtained from high-risk AML patients." (PMID 25092925, 2014). "Using a normal hematopoietic stem cell line HSC2 as a standard, we found that IRAIN was downregulated in leukemia cell lines as compared with the IGF1R sense coding RNA." (PMID 25092925, 2014). "A similar hemi-methylation pattern was also observed in the IRAIN promoter in KG-1 leukemia cells and in three AML samples." (PMID 25092925, 2014). "The association of lncRNAs with several subtypes of leukemia, such as MEG3, IRAIN, and UCA1 related to AML and ANRIL, LUNAR1, in ALL, increase the possibility to use them as biomarkers for the diagnosis, prognosis, and treatment (to provide a target) for the different subtypes of this disease." (PMID 30744139, 2019). "For example, insulin-like growth factor type I receptor antisense imprinted non-protein RNA (IRAIN), which is transcribed antisense to insulin-like growth factor type I receptor (IGF1R) gene, is downregulated in leukemia cell lines and in patients with high-risk AML." (PMID 30744139, 2019).
renal carcinoma (1 paper, 2020). A carcinoma arising from the epithelium of the renal parenchyma or the renal pelvis. "However, the function of lncRNA IRAIN in renal carcinoma (RC) remains enigmatic." (PMID 32983957, 2020).
tumor (10 papers, 2014 to 2023). "In AML, low expression of IRAIN is associated with poor prognosis, suggesting that IRAIN has a tumor-suppressor function." (PMID 36362925, 2022). "A single parental IRAIN allele is transcribed in KG-1 and KG-1a tumor cells." (PMID 25092925, 2014). "It became apparent that tumor size and weight were markedly reduced in mice injected with oe-IRAIN-transfected cells, which was rescued by treatment with oe-VEGFA." (PMID 32983957, 2020). "In conclusion, upregulated lncRNA IRAIN repressed tumor growth of RC through inhibition of VEGFA in vivo." (PMID 32983957, 2020). "LncRNA IRAIN was also able to suppress RC tumor growth via repression of VEGFA in an in vivo mouse xenograft model." (PMID 32983957, 2020). "Overexpression of the IRAIN lncRNA inhibits tumor cell migration, suggesting its tumor suppressor function." (PMID 31653018, 2019). "In this communication, we characterize the allelic expression of IRAIN lncRNA and its role in the formation of interchromosomal interactions in normal and tumor cells." (PMID 25092925, 2014). "As compared with the vector control, expression of the full-length 5.4 kb IRAIN lncRNA significantly inhibited tumor cell migration." (PMID 25092925, 2014). "As a first step to explore the role of IRAIN, we virally expressed the full-length 5.4 kb IRAIN lncRNA in MDA231 tumor cells." (PMID 25092925, 2014). "In contrast to the previous examples, lncRNA IRAIN is downregulated in AML cell lines and patients with high-risk AML, indicating that lncRNAs might not only act as oncogenes but as tumor suppressors in AML, too." (PMID 35596093, 2022). "Finally, the effect of the lncRNA IRAIN/VEGFA axis was confirmed in an in vivo tumor xenograft model." (PMID 32983957, 2020). "IRAIN via targeting IGF1R could alter the phenotypes of MDA-MB-231 tumor cells." (PMID 33768092, 2021). "Stably transfected 786-O cells were inoculated into nude mice in order to explore the effects of lncRNA IRAIN and VEGFA on tumor growth of RC in vivo." (PMID 32983957, 2020). "Thus, the epigenotype in the IRAIN promoter may be aberrantly altered in this tumor line." (PMID 25092925, 2014). "Via employing CRISPRCas9 gene-editing system IRAIN could compete in cis with the overlapping IGF1R promoter, and thereby suppress the IGF1R signaling cascade that in turn attenuate tumor cell proliferation and metastasis in BCa cells." (PMID 33768092, 2021). "As reported, IRAIN may inhibit the activation of insulin-like growth factor type I receptor, which mediates AML cell growth and tumor progression." (PMID 33192510, 2020). "RP11-704M14.1, SFMBT2-4:1, IRAIN, TET2 function as tumor suppressors in AML." (PMID 31681586, 2019).
IRAIN also shares sentences with these, for which no sentence is quoted: metastasis (1 paper); myeloma (1).